IL4 (interleukin 4)
Diseases named in the same sentence as IL4 in open-access papers (continued):
Sharing a sentence is not in itself a finding about the gene and the disease.
tumor (continued). "Interestingly, AMPK deficiency seemed to have minimal influence on the expression of Foxp3, IL-17 and IL-4 in the tumor microenvironment." (PMID 25760243, 2015). "Finally, uPAR controls gene expression in cancer cells, promoting expression of factors such as interleukin-4 and transforming growth factor-β, which condition immune system cells so that the tumor microenvironment is more conducive for tumor growth." (PMID 26283964, 2015). "Importantly, when Th1 differentiation was restored by the blockade of IL-6 or subsequent IL-4/IL-21 activities, induction of tumour-specific aged CD8+ T cells was enhanced as well, implying minimum intrinsic functional defects in aged CD8+ T cells." (PMID 25850032, 2015). "Taken together with our observation that apoptotic cells and IL-4Rα have additive effects in promoting tumor growth (and macrophage accumulation), our results are consistent with roles for IL-4/IL-13 in driving NHL-promoting mechanisms independently of apoptosis." (PMID 25702581, 2015). "Because there are many cytokines in the tumor microenvironment, including IL-4, IL-6, IL-10, and IL-13, we next asked whether these cytokines down-regulated miR-146a and miR-222 in late tumor TAMs." (PMID 26689540, 2015). "Rather than affecting tumor growth in an autocrine fashion, tumor-cell derived IL-4 may have effects on tumorigenesis and metastasis by modulating cells in the tumor niche in a paracrine manner." (PMID 27563494, 2015). "In summary, this study provides novel evidence that IL-4 expression by tumor cells might attenuate their metastatic potential by provoking direct myeloid cell-mediated killing." (PMID 27563494, 2015). "The results presented in this study indicate that morphine may attenuate the invasion-promoting effects of IL-4 or the paracrine interaction between macrophages and cancer in the context of a tumour microenvironment." (PMID 26078009, 2015). "CIC-associated IL-4 was found to be responsible for the production of high levels of immunomodulatory molecules, such as IL-4, and CIC-mediated inhibitory activity to anti-tumor T cell responses." (PMID 25590298, 2015). "The decreased proliferation of CD8+ T cells upon co-culture with IL-4- and TNFα-pretreated tumor cells could be partially converted by the use of an anti-B7-H1 blocking antibody as proof for the inhibitory role of B7-H1 on tumor cells." (PMID 24885059, 2014). "IL-4 may also upregulate the antiapoptotic protein level, thereby reducing the killing ability towards tumor cells." (PMID 25202391, 2014). "Therefore, IL-4 is thought to have a potent anti-tumor effect in vivo against various types of cancer by inducing an immune response." (PMID 26056588, 2014). "In the present studies focal irradiation of the tumor reduced the Th2 (IL-4 and IL-5) responses through B cells and inflammation (IL-6, IL-17, GM-CSF, IL-1α), which was accentuated by 2-DG besides removing the systemic immunosuppression through depletion of Tregs." (PMID 25248151, 2014). "Early work suggested that IL-4 may promote anti-tumor effects of CD8+ tumor-infiltrating lymphocytes and promote persistence of CD8+ T cells." (PMID 25207963, 2014). "In addition, CTL-derived cytokines, including tumor necrosis factor α, interleukin 4 (IL-4) and IL-10, contribute to tumor rejection by inhibition of tumor stroma formation." (PMID 25289108, 2014). "Furthermore, IL-4 has a tremendous impact on the anti-tumor immunity by shifting the Th1/Th2 balance." (PMID 24885059, 2014). "Because myeloid cells can show a high plasticity among which macrophages, it should be investigated whether addition of different stimuli, e.g. IL-4, GM-CSF, M-CSF or tumor-conditioned medium to the MuMac-E8 cell line gives rise to distinct cell types." (PMID 25546418, 2014).
tumor (continued). "To assess the possible roles of these cytokines in the suppressive activity of IMCs in the bone marrow of non-tumor-bearing mice, we added neutralizing antibodies to IL-4, IL-10 and TGFβ1 to cultures of mitogen activated T-cells co-cultured with CD11b+GR-1+ IMC." (PMID 23843936, 2013). "The IL4 pathway was significantly enriched in both tumor progression and chemotherapy signatures." (PMID 23451142, 2013). "The intersection of tumor progression and chemotherapy signatures in immune cells suggest that the IL4 pathway may play a potential role in the immune surveillance of NSCLC tumorigenesis, and immune potentiation of combination chemotherapy for NSCLC." (PMID 23451142, 2013). "Thus, delivery stimulator such as CD80, interleukin-4 (IL-4), and cytokines by intelligent nanocarriers to tumor microenvironment can produce T-cell priming with the microenvironment reversion." (PMID 24369011, 2013). "Peripheral blood mononuclear cells obtained by leukapheresis were cultured with granulocyte-macrophage colony-stimulating factor, interleukin-4, OK-432 and prostaglandin E2 to generate DCs, which were pulsed with autologous tumor lysates or tumor-specific peptides, such as WT1." (PMID 24649223, 2013). "However, it has previously been reported that Th2 cells can have anti-tumour activity, possibly through IL-4 and the recruitment of innate immune cells." (PMID 23717511, 2013). "The subsequent secretion of type 2 cytokines such as IL-4 and IL-13 may actually serve to accelerate tumor growth and prevent tumor cell apoptosis." (PMID 23606870, 2013). "Factors that are known to promote SCC progression and have been associated with poor prognosis included CCL22, a chemokine that attracts regulatory T cells (Tregs) that shut down the anti-tumor immune response, IL-10, an immuno-regulatory/suppressive cytokine, and IL-4, a prototypical Th2 cytokine." (PMID 22558071, 2012). "In other studies, the investigators observed that IL-4 and IL-13 can inhibit the tumor regression." (PMID 23108822, 2012). "The increase in IL-10 and IL-4 release on group P animals may enhance the host immune response against the tumor and aid in the control of tumor growth." (PMID 22827934, 2012). "In contrast, IL4-producing Th2 cells may promote tumor progression by enhancing the activity of protumor macrophages although Th2 cells can also mediate tumor rejection under certain condition." (PMID 22400040, 2012). "Thus, while IL-4 clearly induces M2 polarization as described, co-cultures of fibroblasts, macrophages and tumor cells also contain factors able to activate macrophages towards an M2 phenotype after prolonged exposure." (PMID 22792213, 2012). "Results showed that a high-anxious behavioral phenotype characterized in the EPM but not the LDA was associated with higher tumor counts, higher IL-4 gene expression in UV exposed skin, and higher total adrenal corticosterone concentrations." (PMID 22558071, 2012). "As would be expected, TAMs possess M2-like traits; Tumour cells and the tumour microenvironment release a variety of factors that facilitate this, including IL-4, IL-6, IL-10, PGE2, TGF-β1 and CSF-1, expressed by tumour cells, as well as IL-10, PGE2 and MMP-7 expressed by TAMs." (PMID 22005011, 2011). "In addition to direct actions upon tumor cells, emerging evidence indicates that IL-4 also exerts pro-tumorigenic indirect effects, mediated via the tumor microenvironment." (PMID 24213139, 2011). "Interestingly, M2 macrophages (derived from direct tumor cell contact and IL4, IL10 and IL13 exposure) drive a Th2 response resulting in increased expression of anti-inflammatory cytokines and down-regulation of pro-inflammatory mediators." (PMID 21629653, 2011).
tumor (continued). "Studies in colon, breast, lung, fibrosarcoma, prostate and bladder cancer models indicate that IL-4 is not only produced by many cultured tumor cell lines, but that its interaction with IL4-Rα leads to the up-regulation of anti-apoptotic molecules such as cFLIP, PED, FLAME-1 and Bcl-x(L)." (PMID 24213139, 2011). "Pre-clinical work has shown a complex and at times contradictory role for IL-4 in tumor immunity." (PMID 24213139, 2011). "Th2 polarization is dependent upon, and leads to, production of IL-4 which might have direct immunosuppressive effects on CD8+ T cells at the tumor site." (PMID 21943203, 2011). "These Th0 cells may produce IL-2, IFN-γ as well as IL-4 and may evolve in the tumor microenvironment depending on the danger signals provided in such environment." (PMID 21943203, 2011). "These experiments demonstrate that IL-4-mediated suppression of tumor growth may be due to IL-4s ability to inhibit angiogenic processes." (PMID 20445741, 2010). "There is also evidence that IL-4 inhibits neovascularization, thus inhibiting tumor growth." (PMID 20445741, 2010). "We next evaluated whether the observed IL-4-mediated and tumor-induced suppression of miR-17-92 are relevant in human T cells." (PMID 20167088, 2010). "Additionally, receptors for IL-4 are expressed by many human tumor types and have been shown to promote the proliferation of tumor cells." (PMID 19956757, 2009). "The ability of IL-4 to inhibit IL-2 gene transcription has been confirmed by other researchers, suggesting that the elevation of IL-4 production during an ongoing immune response to tumor can down-regulate Th1 cytokine production." (PMID 19138398, 2009). "To determine whether VEGFR-2 expression on pCSCs is regulated by tumor environmental cues, we examined the effects of cytokines on the expression in vitro., including Flt3 ligand (FL), GM-CSF, IL-3, IL-4, IL-6, IL-7 and IL-13." (PMID 18286204, 2008). "Providing ex vivo generated DC may be a strategy to overcome some of these obstacles with the added advantage of DC cultured in GM-CSF and IL-4 may be more resistant to the suppressive effects of the tumor microenvironment." (PMID 18644162, 2008). "Furthermore, the cytokines IL-2, IL-4, TNFα and IFNγ have been shown to inhibit tumor-induced angiogenesis in some animal models by inhibition of tumor stroma formation." (PMID 19578507, 2008). "Interleukin-4 (IL-4) is an immunomodulatory cytokine, which can inhibit the growth of tumour cells." (PMID 15714203, 2005). "Immunohistochemical analysis of tumour nodules undergoing regression showed stimulation of a largely lymphocytic infiltrate by IL-2 and a macrophage and granulocyte infiltrate, with a small number of lymphocytes by IL-4." (PMID 8347485, 1993). "Additionally, we find that PSMA Ab, EGFR Ab, or PSMA.CAR10.3 increase in vitro phagocytosis of Myc-CaP cells expressing PSMA or EGFR by p50-IMC-derived macrophages, including in M2-promoting IL-4, which is a component of the immune-suppressive tumor microenvironment." (PMID 39904797, 2025). "Furthermore, circWWC3 may facilitate BC progression by inducing M2 macrophage polarization and tumor immune evasion through the upregulation of interleukin-4 (IL-4) expression and secretion." (PMID 40718834, 2025). "Notably, α-HB subtype 2 exhibited significant enrichment in various immune and inflammatory pathways, including regulation of response to tumor cells, synaptic vesicle localization, and multiple interleukin-mediated signaling pathways (such as IL-6, IL-4, IL-2, and IL-15)." (PMID 41041634, 2025). "This dual behavior reflects an insufficient anti-inflammatory counterbalance in the tumor-driven pro-inflammatory environment, where compensatory increases in IL-4 and IL-10 may become saturated, thereby limiting their regulatory capacity and contributing to cancer-related cognitive dysfunction." (PMID 41155372, 2025).
tumor (continued). "In addition, tumor cell-derived lactate impairs the function of natural killer T cells by inhibiting the mTOR signaling pathway and nuclear translocation of zinc finger proteins, resulting in reduced secretion of IFN-γ and IL-4 and significantly weakened anti-tumor effect." (PMID 40045411, 2025). "In addition to secreting IL-17A to promote tumor growth, γδ T cells also produce IL-4." (PMID 40558272, 2025). "In line with current concepts that tumor-associated macrophages represent pre-educated, polarized or hybrid states rather than true M0 cells, our study therefore focused on how TTFields modulate IFN-γ-primed and IL-4–polarized macrophages as more relevant surrogates of TAM subsets." (PMID 41465516, 2025). "Eosinophils and mast cells might inhibit Th1 anti-tumor immunity by releasing Th2 cytokines such as IL-4 and IL-13, but their metabolic pathways (such as cytochrome P450) that were highly expressed at the same time might play a protective role by clearing carcinogens." (PMID 40568599, 2025). "Interestingly, IL-4 has been suggested to slow the proliferation of solid tumor cells, especially in LC, and may hinder tumor angiogenesis." (PMID 41179937, 2025). "In addition, tumor proliferation, invasion and metastasis are enhanced by IL-4-activated." (PMID 41376630, 2025). "Moreover, IL-4 exerts a profound influence on the microenvironment of the tumor." (PMID 40507238, 2025). "Notably, combining anti-PD-1 therapy with either a genetic IL-4 KO in tumor cells or with an FDA-approved IL4R-blocking antibody in a clinically relevant OvCa mouse model delayed tumor progression underscoring the translational potential of this strategy as a therapeutic approach." (PMID 39837825, 2025). "Moreover, the interaction between B cells and TNBC tumor cells, leading to an upregulation of the inflammatory cytokines IL-4 and IL-10 that drive the chronic inflammatory response of the tumor, may impede the antibody-mediated immune response." (PMID 40079015, 2025). "More critically, by inhibiting IL-4 mRNA expression in the livers of patients with PC malignancy and by improving the physical condition of IL-4-treated tumor-bearing mice, it may provide a potentially effective approach for the future treatment of PC patients with tumor-induced malignancy." (PMID 39958351, 2025). "However, eosinophils may also promote tumor progression through their ability to release cytokines and growth factors such as IL-4, IL-5, and vascular endothelial growth factor (VEGF), which can support angiogenesis and tumor evasion." (PMID 40272538, 2025). "Recent findings suggest that IL-4 neutralization can enhance anti-tumor immunity by reducing the generation of immunosuppressive M2 macrophages and myeloid-derived suppressor cells, while increasing tumor-specific cytotoxic T lymphocytes, thus delaying tumor progression." (PMID 39125732, 2024). "However, IL-33 neutralisation in vivo led to a more quiescent tumour characterised by the infiltration of CD4+ T cells producing interferon gamma (IFNγ) (Th1-like) and decreased Th2-like cells (CD8+ and CD4+ T cells expressing IL-4) in the tumour microenvironment." (PMID 38662248, 2024). "However, macrophage polarization states are highly dynamic and M1-like TAM readily acquire a M2-like phenotype when exposed to immune-suppressive cytokines like interleukin 4 (IL4), IL10, transforming growth factor β (TGFβ) and to hypoxia, conditions associated with tumor growth and progression." (PMID 39056192, 2024). "Therefore, although using IL-4 to improve tumour immunity may initially seem counter-intuitive, it may be worth testing experimentally whether IL-4 can arrest proliferation of immunosuppressive TAMs and improve anti-tumour immune activity." (PMID 38903497, 2024). "Indeed, cancer patients often exhibit elevated levels of IL-4 in the tumor microenvironment." (PMID 39452870, 2024).
tumor (continued). "In addition, the excessive production of vascular endothelial growth factor (VEGF) is positively correlated with elevated levels of IL-4, indicating that IL-4 may support tumor progression through different mechanisms." (PMID 38903721, 2024). "Importantly, in vitro antibody-mediated neutralisation of ILC2-derived IL-4 and IL-13 reduced tumour MDSC Arg1 levels, and similarly genetic deletion of IL-13 in mice with CRC decreased Arg1+ MDSCs, increased IFNγ production by Th1 cells and CD8+ T cells, and significantly reduced tumour burden." (PMID 38464388, 2024). "Furthermore, treating THP‐1 cells with PMA + IL‐4 + IL‐13 for 72 h resulted in a decrease in Wnt5a protein expression in HCT116 cells, which may be associated with its involvement in tumor cell differentiation‐related functions." (PMID 39302044, 2024). "Previous study has demonstrated that ILC2s secrete the characteristic cytokines IL-13 and IL-4, which facilitate tumor progression by facilitating the recruitment of monocyte-derived myeloid suppressor cells (MDSCs), which plays a crucial role in suppressing anti-tumor immune responses." (PMID 38430390, 2024). "Interleukin-4 is an immunomodulatory cytokine that plays a dual role in the pathogenesis of tumor development, exhibiting both antiangiogenic and immunosuppressive properties, which may facilitate tumor progression by creating an appropriate immune environment." (PMID 39334861, 2024). "MCP-1 binding to its receptor CCR2 activates monocytes and induces leukocyte infiltration, as well as T-cell proliferation; it acts also as a regulator in the polarization of Th0 cells toward a Th2 phenotype and, coupled with IL-4 signaling, it could contribute to tumor growth and metastasis." (PMID 38443899, 2024). "Moreover, rhPOSTN-treated tumor cells had a higher IL-4 level than PBS-treated cells." (PMID 38773979, 2024). "However, since IL-4 is the main mediator of Th2 differentiation and is also involved in their antitumor effect, several studies have attempted to mimic this signaling in the tumor microenvironment." (PMID 36980536, 2023). "TAMs at the tumor site, stimulated by different cytokines, differentiate into M1-type macrophages (pro-inflammatory phenotype) with anti-tumor effects or M2-type macrophages (anti-inflammatory phenotype) that inhibit anti-tumor effects and release IL-4, IL-10, and IL-13." (PMID 37055849, 2023). "TME consists of myeloid suppressor cells, tumor-associated macrophages and Treg-secreting cytokines that inhibit the anti-cancer response, and soluble immunosuppressive factors (transforming growth factor beta (TGF-β), interleukin 4, indoleamine 2,3-dioxygenase)." (PMID 37296906, 2023). "Importantly, whether the maximally tolerated dose of IL-4 injected in patients is sufficient to elicit anti-tumour properties is unclear." (PMID 37455828, 2023). "Finally, an overexpression of this miR leads to a reduced JAK1, STAT6, and AKT phosphorylation and IL-4-induced migration and invasion; this, together with data from the literature, leads to the conclusion that miR-494-5p is an early tumor and initial metastasis suppressor in CRC." (PMID 38201452, 2023). "Th2 is one of the special subtypes of CD4+ helper T cell (Th cell) that mainly secretes cytokines such as IL-4, IL-5, and IL-10, and excessive Th2 cells could affect the tumour-suppressive immune microenvironment, seriously reducing the anti-tumour effect, leading to the malignant growth of tumours." (PMID 35591854, 2022). "Therefore, and since we observed no significant increase of Tgfb1 mRNA expression or of FoxP3+CD4+ Tregs in βΑ tumors, we wondered whether Activin-A stimulates tumor growth by promoting IL4 signaling." (PMID 35580932, 2022).